TLN2 (talin 2)
Description:
As a major component of focal adhesion plaques that links integrin to the actin cytoskeleton, may play an important role in cell adhesion. Recruits PIP5K1C to focal adhesion plaques and strongly activates its kinase activity (By similarity).
Synonyms: KIAA0320; ILWEQ
Tractability: Antibody: UniProt places it where antibodies can reach, with medium confidence; its Gene Ontology location is reachable by antibodies, with medium confidence. PROTAC: ubiquitination databases record sites on it; its protein half-life has been measured.
Gene: Protein-coding gene on chromosome 15 (62,390,512 to 62,844,631, forward strand). Ensembl gene ENSG00000171914.
Subcellular location: Cytoplasm; Cell junction, focal adhesion; Synapse; Cell membrane; Cytoplasm, cytoskeleton
Subcellular location (Human Protein Atlas): Cytosol; Focal adhesion sites
Gene Ontology:
Molecular function: protein binding; actin binding; integrin binding; structural molecule activity; actin filament binding; structural constituent of cytoskeleton
Biological process: presynaptic actin cytoskeleton organization; actin cytoskeleton organization; cell adhesion; cell-cell adhesion; cell-cell junction assembly
Cellular component: cytoplasm; cytosol; focal adhesion; synapse; actin cytoskeleton; plasma membrane; cytoskeleton; ruffle
Genetic constraint (gnomAD): Loss-of-function variants: 111 observed, 284.73 expected, observed/expected ratio (o/e) 0.39, 90% interval 0.33 to 0.46. The upper end of that interval is the gene's LOEUF score, 0.46, which puts it in group 2 of 6, group 1 being the genes least tolerant of losing a copy. Missense variants: 2,992 observed, 3,305 expected, observed/expected ratio (o/e) 0.91, 90% interval 0.88 to 0.93. Synonymous variants: 1,400 observed, 1,322.7 expected, observed/expected ratio (o/e) 1.06, 90% interval 1.01 to 1.11.
Homologues: Orthologues: chimpanzee TLN2 (99% identical), guinea pig TLN2 (99% identical), dog TLN2 (99% identical), pig TLN2 (99% identical), mouse Tln2 (99% identical), rat Tln2 (99% identical), rabbit TLN2 (98% identical), macaque TLN2 (97% identical), tropical clawed frog tln2 (92% identical), zebrafish tln2a (87% identical), zebrafish tln2b (51% identical), Drosophila melanogaster rhea (48% identical), and 1 more. Paralogues in human: TLN1 (76% identical), TLNRD1 (4% identical).
Diseases named in the same sentence as TLN2 in open-access papers:
TLN2 is named in the same sentence as 32 diseases in open-access papers, as found by Europe PMC text mining. Sharing a sentence is not in itself a finding about the gene and the disease. The quoted sentences say what the papers report.
breast carcinoma (6 papers, 2012 to 2022). "TLN2 is an intracellular cytoskeletal protein, a major component of the focal adhesion complex, involved in breast cancer and hepatocellular carcinoma." (PMID 34660294, 2021). "Considering that TLN2 shares 76% protein sequence identity with TLN1, we analysed the expression of TLN2 in the breast cancer dataset from TCGA database." (PMID 35285795, 2022). "Our study has identified another miRNA (miR-194) and new target (talin 2, motility) in HER2-overexpressing breast cancer cells." (PMID 22829924, 2012). "Previous studies have shown that SRPX2 and SPARC were overexpressed in gastric cancer tissues, while TLN2 was upregulated in breast carcinomas tissues; however, no studies investigating the expression of TLN2, SRPX2, and SPARC in peripheral blood have been reported." (PMID 23548070, 2013).
glioma (3 papers, 2021 to 2024). A benign or malignant brain and spinal cord tumor that arises from glial cells (astrocytes, oligodendrocytes, ependymal cells). "For example, we constructed a lncRNA–miRNA–mRNA network to uncover the potential significance of Prostate Androgen-Regulated Transcript 1 (PART1)-hsa-mir-25-Talin 2 (TLN2)/Zinc Finger DHHC-Type Palmitoyltransferase 8 (ZDHHC8) in glioma." (PMID 39857625, 2024). "The interaction between PART1-hsa-mir-25-SLC12A5/TACC2/BSN/TLN2/ZDHHC8 is largely unclear in glioma and requires further analysis." (PMID 34660294, 2021). "SLC12A5/TACC2/BSN/TLN2/ZDHHC8 was downregulated in patients with glioma with poor OS." (PMID 34660294, 2021).
atherosclerosis (2 papers, 2020 to 2023). A disease characterized by the build-up of fatty material and calcium deposition in the arterial wall resulting in partial or complete occlusion of the arterial lumen. "Moreover, downregulation of the TLN2 gene has been associated with atherosclerosis in human arterial plaque tissue samples." (PMID 37370144, 2023). "The hub gene TLN2 is thought to be involved in atherosclerosis." (PMID 33304381, 2020). "Experimental manipulation of DNA methylation in engineered human umbilical vein endothelial cells indicated that the identified differentially methylated probes located at TRIM6, TLN2, and FLRT2 genes may play a role in endothelial cell adhesion and atherosclerosis." (PMID 37370144, 2023).
Camptodactyly (2 papers, 2016 to 2022). The distal interphalangeal joint and/or the proximal interphalangeal joint of the fingers or toes cannot be extended to 180 degrees by either active or passive extension. "In summary, our results not only reveal that TLN2 mutation is associated with isolated camptodactyly in a Chinese Han family but also confirm genetic heterogeneity in this disorder." (PMID 27223613, 2016). "In this study, a heterozygous mutation, p.S339L, in the TLN2 gene was identified in a large Chinese Han pedigree with nonsyndromic camptodactyly." (PMID 27223613, 2016). "Our data suggest a potential molecular link between TLN2 and camptodactyly pathogenesis." (PMID 27223613, 2016).
gastric cancer (2 papers, 2013 to 2020). A primary or metastatic malignant neoplasm involving the stomach. "In this study, we detected the expression of KAP1, TIMP1, STC2, TLN2, SRPX2, integrin beta 1 (ITGB1) and SPARC mRNAs in peripheral blood samples from pre-operative gastric cancer patients, patients with recurrence, and healthy volunteers." (PMID 23548070, 2013). "In this study, we detected the expression levels of KAP1, TIMP1, STC2, TLN2, SRPX2 and SPARC mRNAs in peripheral blood samples from pre-operative gastric cancer patients, those with recurrence, and in healthy volunteers." (PMID 23548070, 2013). "Our study showed that TLN2, SRPX2 and SPARC expression were detected in gastric cancer, but expression of TLN2, SRPX2 and SPARC could not differentiate preoperative gastric cancer patients from healthy volunteers." (PMID 23548070, 2013).
hepatocellular carcinoma (2 papers, 2016 to 2021). A malignant tumor that arises from hepatocytes. "Talin-1 (TLN-1) and TLN-2 are implicated in many cellular processes, but their roles in hepatocellular carcinoma (HCC) remain unclear." (PMID 26822056, 2016).
prostate carcinoma (2 papers, 2018 to 2023). A carcinoma that arises from epithelial cells of the prostate gland. "Furthermore, TLN2 hosts another microRNA, miR-132, which also targets FOXP2 transcripts, and has been widely reported as being involved during prostate cancer progression." (PMID 29725501, 2018).
Alzheimer ́s disease (1 paper, 2022). "The talin 2 gene (TLN2) codes for a cytoskeleton protein that participates in cellular adhesion, and it was found to be associated with Alzheimer ́s disease." (PMID 36140716, 2022).
cardiomyopathy (1 paper, 2021). A disease of the heart muscle or myocardium proper. "Other studies focusing on a Han population found an association between a prognosis of heterogeneous cardiomyopathy with SNPs associated with LGALS3, AGCT, SLC25A13, HRG, APOB, SOD3, SYNM, and TLN2." (PMID 34572079, 2021).
Duchenne muscular dystrophy (1 paper, 2016). Duchenne muscular dystrophy (DMD) is a neuromuscular disease characterized by rapidly progressive muscle weakness and wasting due to degeneration of skeletal, smooth and cardiac muscle. "Tln2 diminished in masseter and temporal muscle of mdx mice, a model of Duchenne muscular dystrophy." (PMID 27223613, 2016).
ischemic stroke (1 paper, 2023). A stroke disorder caused by obstruction of blood flow to the brain, due to thrombotic (local blood clot formation) or embolic (due to a blood clot or other material traveling from another site) event. "Altered DNA methylation of the TRIM6, TLN2, and FLRT2 genes may play a functional role in ischemic stroke in Chinese populations." (PMID 37370144, 2023).
kidney cancer (1 paper, 2024). Primary or metastatic malignant neoplasm involving the kidney. "Prior research indicated that TLN2 suppressed kidney cancer by inhibiting the Wnt/β-catenin signaling pathway, Yet Fang’s study contradicted this finding." (PMID 38751445, 2024).
liver cancer (1 paper, 2024). An epithelial or non-epithelial malignant neoplasm that arises from the liver. "Suggested that the presence of TLN2 was linked to the cancer-causing potential of liver cancer cells." (PMID 38751445, 2024).
multiple endocrine neoplasia type 2 (1 paper, 2024). Multiple endocrine neoplasia type 2 (MEN2) is a multiple endocrine neoplasia, a polyglandular cancer syndrome characterized by the occurrence of medullary thyroid carcinoma (MTC), pheochromocytoma (PCC), in one variant, primary hyperparathyroidism (PHPT). "Finally, we highlight a talin 1 and 2 (TLN1 and TLN2) PTB binding site in the proto-oncogene tyrosine-protein kinase receptor Ret (RET), which is disrupted by two mutations (L1061P, Y1062A) linked to multiple endocrine neoplasia type 2 and to different types of tumours." (PMID 39009827, 2024).
myelofibrosis (1 paper, 2009). A partial or complete replacement of the bone marrow stroma by fibrous tissue. "Interestingly, miR-190 is expressed in mouse testis and kidney, where the two Tln2 short transcripts are highly expressed, as well as in various human cell lines, and is upregulated in primary myelofibrosis patients." (PMID 19220457, 2009).
pulmonary stenosis (1 paper, 2020). "We also report novel plausible gene–disease associations for tetralogy of Fallot/pulmonary stenosis (CDC42BPA, FGD5), hypoplastic left or right heart (SMARCC1, TLN2, TRPM4, VASP), congenitally corrected transposition of the great arteries (UBXN10), and early-onset cardiomyopathy (TPCN1)." (PMID 32037394, 2020).
Stroke (1 paper, 2023). Sudden impairment of blood flow to a part of the brain due to occlusion or rupture of an artery to the brain. "In the present study, we found that stroke patients were characterized by TLN2 hypermethylation, while in vitro modulation of DNA methylation at the TLN2 locus via CRISPR/dCas9-Dnmt3a system revealed a positive association between TLN2 methylation and TLN2 expression." (PMID 37370144, 2023). "However, findings from our CRISPR/dCas9-Dnmt3a cell model suggest that the observed DNA methylation changes have antagonistic effects suggesting that we identified a mixture of stroke inducing (e.g., TRIM6 gene) as well as neuroprotective (e.g., TLN2 and FLRT2 genes) epigenetic biomarkers." (PMID 37370144, 2023).
cancer (9 papers, 2015 to 2024). A tumor composed of atypical neoplastic, often pleomorphic cells that invade other tissues. "The expression of TLN1 and TLN2 was positively associated with CNV in most cancers, except for APBB1IP, RAP1B, and RAP1A." (PMID 33391455, 2021). "TLN2 is a coding gene which has been reported to be involved in cancer metastasis." (PMID 32256587, 2020). "No change in cell viability could be due to varied conditions of cell growth, low siRNA dosage for this aggressive cell line, or upregulation of another isoform of talin, talin-2 whose role has been found in certain cancers." (PMID 31269666, 2019). "In the past decades, a large number of studies have demonstrated the biological function of TLN1 in the development of several types of cancers, including GC, but there is little evidence with regard to the role of TLN2 in GC metastasis." (PMID 32256587, 2020).
tumor (4 papers, 2020 to 2024). "It demonstrated a notably elevated expression of SERPINA1, RASGRP1, and CFB in tumor tissues, while C1S and TLN2 showed significantly higher expression in normal tissues." (PMID 38751445, 2024). "The EMX2OS/hsa‐miR‐31‐5P/TLN2 axis might yield functional impact on tumor microenvironment in ccRCC and may represent a novel therapeutic target for ccRCC." (PMID 38808948, 2024). "On this basis, we built the relevant ceRNA network and found that EMX2OS might have an important function in the ccRCC tumor microenvironment through the EMX2OS/hsa‐miR‐31‐5P/TLN2 axis." (PMID 38808948, 2024). "Our findings revealed that lnc-TLN2-4:1 upregulation can significantly inhibit the migration and invasion of GC cells but does not affect GC cell proliferation, suggesting that lnc-TLN2-4:1 acts as a tumor suppressor in GC metastasis." (PMID 32256587, 2020). "These suggest that lnc-TLN2-4:1 may be a tumor suppressor during GC metastasis." (PMID 32256587, 2020). "Specifically, tumor tissues show increased expression of SERPINA1, RASGRP1, and CFB compared to normal tissues, whereas C1S, SERPINF2, and TLN2 display the opposite pattern." (PMID 38751445, 2024).
myopathy (1 paper, 2019). A disease of the muscle in which the muscle fibers do not function properly. "Mouse mutants of talin 1 or talin 2 perform myopathy and disassembly of the sarcomeres." (PMID 31623094, 2019).
TLN2 also shares sentences with these, for which no sentence is quoted: adenocarcinoma (1 paper); cardiac hypertrophy (1); delirium (1); dilated cardiomyopathy (1); gastric tumor (1); heart failure (1); lung adenocarcinoma (1); lymph node metastasis (1); metastasis (1); muscular dystrophy (1); pulmonary arterial hypertension (1); Tetralogy of Fallot (1).